SLC25A25-AS1 (SLC25A25 antisense RNA 1)
Synonyms: HRCEG
Gene: Long non-coding RNA gene on chromosome 9 (128,108,581 to 128,118,693, reverse strand). Ensembl gene ENSG00000234771.
Diseases named in the same sentence as SLC25A25-AS1 in open-access papers:
SLC25A25-AS1 is named in the same sentence as 2 diseases in open-access papers, as found by Europe PMC text mining. Sharing a sentence is not in itself a finding about the gene and the disease. The quoted sentences say what the papers report.
colorectal cancer (1 paper, 2018). A primary or metastatic malignant neoplasm that affects the colon or rectum. "In addition, lncRNA SLC25A25 antisense RNA 1 (SLC25A25‐AS1) was recently found to be dysregulated and associated with cell proliferation and chemoresistance in colorectal cancer, suggesting its similar function in gastric cancer." (PMID 29992774, 2018).
SLC25A25-AS1 also shares sentences with these, for which no sentence is quoted: gastric cancer (1 paper).